AXL (AXL receptor tyrosine kinase)
Diseases named in the same sentence as AXL in open-access papers (continued):
Sharing a sentence is not in itself a finding about the gene and the disease.
tumor (continued). "In the study, not only the number of CD4+ and CD8+ T cells significantly increased, but also the gene expression associated with type 1 T-cell recruitment and functionality enhanced when AXL is inhibited in R428-treated tumor-bearing mice." (PMID 34778071, 2021). "We investigated the mRNA expression levels of AXL to identify differential expression patterns between tumor tissue and adjacent non-tumor renal tissue in TCGA pan-cancers." (PMID 34838035, 2021). "To assess the potential anti-tumor activity of dual inhibition of AXL and TGFβ receptors we performed a colony-forming and migration assay in HCT116 and LoVo cells." (PMID 33570712, 2021). "The dual role of AXL in tumour and immune cells explains the reason why AXL inhibition synergizes with such a broad spectrum of therapeutic agents." (PMID 34638349, 2021). "AXL blockade of MG63.2 cells by SGI-7079 significantly reduced tumor bioluminescence and the number of pulmonary metastases." (PMID 33408328, 2021). "Next, we evaluated the efficacy of gilteritinib by mouse xenograft tumor model using AXL-overexpressed H3122 cells." (PMID 33627640, 2021). "The annexin II-mediated link between tumor cells and osteoblasts promotes the expression of tyrosine kinase receptors AXL, Sky, and Mer on tumor cells, whose ligand is GAS6." (PMID 34212564, 2021). "As expected, compared with HUVEC cells, HUVEC AXL-OE cells significantly increased AXL expression in the tumor tissue of xenograft mice subcutaneously inoculated with HCC-LM3 cells and MHCC-97L cells in vivo." (PMID 34123800, 2021). "Several studies have revealed that GAS6/AXL signaling plays a vital role in promoting the immune-suppressive tumor microenvironment." (PMID 34778071, 2021). "In this study, the molecular mechanism of AXL expressed in tumor-derived endothelial cells (TECs) in vessel metastasis was investigated." (PMID 34123800, 2021). "It has been reported that the PI3K/AKT signaling pathway plays a critical role in tumor angiogenesis and can be modulated by AXL." (PMID 34123800, 2021). "While mice treated with either Panobinostat or Mocetinostat showed reduced xenograft tumor growth, the expression of established invasiveness genes, such as AXL or NGFR was upregulated." (PMID 34417458, 2021). "While AXL expression in tumors is readily recognized, it is less well known that AXL is expressed by various cells found in the tumor microenvironment, which include several immune cell types, fibroblasts, osteoclasts, and endothelial cells." (PMID 34778071, 2021). "Activation of AXL can enhance tumor-promoting processes such as cancer cell proliferation, migration, invasion and survival." (PMID 34439388, 2021). "Targeting AXL were shown to sensitize tumours to various types of therapies, including DNA damaging agents, EGFR, VEGFR, HDAC, G2/M checkpoint, and immune checkpoint inhibitors." (PMID 34638349, 2021). "Immunoreaction in tumor cells was detected in 30 cases (28%; range, 5%–80%) and in 17 cases (16%; range, 5%–50%) for AXL and RIPK3, respectively." (PMID 34745951, 2021). "Then, using AXL expressed H3122 cells, we revealed gilteritinib significantly suppress cell survival and tumor regrowth compared to alectinib." (PMID 33627640, 2021). "The authors stated that AXL and Mer are expressed in several tumor cells and have their oncogenic role well established, but their gene silencing led to an increase of post-inflammatory cytokines, favoring a tumor-promoting environment." (PMID 33759958, 2021). "We also found that the patients with high AXL expression in TECs also had lower OS (p = 0.033) compared with those with high AXL expression in tumor cells." (PMID 34123800, 2021). "Activation of AXL signaling in hybrid EMT/MET tumour cells will have several important consequences." (PMID 34638349, 2021). "It has been reported that the PI3K/AKT signaling pathway has a critical role in tumor angiogenesis and can be modulated by AXL." (PMID 34123800, 2021).
tumor (continued). "The results showed that treatment with the AXL inhibitors successfully inhibit AXL activation in vitro and significantly reduce tumor growth in orthotopically implanted RCC, thus support their clinical relevance and warrant future clinical testing." (PMID 34877810, 2021). "Compared with the normal tissue, the AXL expression was significantly increased in ccRCC tumor tissue (P < 0.001)." (PMID 34838035, 2021). "Two additional anti-AXL mAbs (D9 and E8) decreased AXL expression by promoting AXL internalization, resulting in inhibition of proliferation and migration in vitro and reduced tumor growth in murine models." (PMID 34830794, 2021). "AXL is a potential driver of various cellular processes, including tumor proliferation, metastasis, and resistance to targeted therapies." (PMID 34572484, 2021). "Tumor suppressor miR-515-3p can regulate oxaliplatin sensitivity by targeting AXL Receptor Tyrosine Kinase (AXL)." (PMID 34512721, 2021). "Pharmacologic AXL inhibition using a selective AXL inhibitor (R428 or SGI-7079) in tumor cells of C57BL/6 mice significantly increased the expression of PD-1 and MHC-I molecules." (PMID 34778071, 2021). "Downregulation of AXL expression attenuated cell proliferation, migration, and invasion in vitro and inhibited tumor metastasis in vivo." (PMID 34948046, 2021). "Consistent with TCGA results, AXL was up-regulated in ccRCC tumor tissues and related to significant OS (all P < 0.05)." (PMID 34838035, 2021). "It presented that the AXL total protein expression was elevated in primary tumor tissue than in adjacent non-tumor renal tissue (P < 0.001)." (PMID 34838035, 2021). "The binding of Gas6 to AXL induces pathways involved in tumor cell growth, invasion, EMT, angiogenesis, drug resistance, immune regulation, and CSC maintenance." (PMID 33805447, 2021). "In this regard, our group has previously demonstrated that the blocking of AXL with foretinib exhibits anti-tumor activity since it reduces cancer cell survival and migration capability in vitro and determines tumor regression in vivo." (PMID 33570712, 2021). "In concordance with these data, AXL inhibition greatly increased the infiltration, activation, and proliferation of tumor-infiltrating CD4+ and CD8+ T cells and reduced the infiltration of TAMs." (PMID 33922556, 2021). "Several engineered AXL decoy receptors with 80-fold higher affinity for GAS6 compared to the wild-type AXL receptor significantly reduced tumor burden and metastasis in vivo." (PMID 34830794, 2021). "HUVEC invasion and angiogenesis in the matrigel plug assay were activated by S100A10, while AXL inhibition reduced tumor progression and vessel density in ccRCC tumor xenografts and PDX models." (PMID 34209679, 2021). "A growing number of evidence indicated the AXL gene played an important role in tumor development, metastasis, stem cell phenotype, drug resistance, and prognosis." (PMID 34838035, 2021). "To limit our analysis only to tumor cells, we analyzed AXL expression only in cells that were CD45−, CD31−, and EPCAMmid/high." (PMID 34254585, 2021). "AXL is an attractive and novel therapeutic target for impairing tumor progression from immune cell contracts in the tumor microenvironment." (PMID 34778071, 2021). "In endothelial cells, AXL expression is involved in vascularization; i.e., when it is inhibited in tumor-bearing mice, it leads to the inhibition of tumor-induced angiogenesis." (PMID 34778071, 2021). "This study reminds us that although anti-tumor compounds enhance ROS production in providing CP sensitivity, it should be noted that ROS can activate downstream targets with tumor-promoting roles such as AXL." (PMID 33921908, 2021). "Association between AXL and RIPK3 immunoreactivity and clinical–pathological variables, sentinel lymph node status, and tumor-infiltrating lymphocytes (TILs) was assessed." (PMID 34745951, 2021).
tumor (continued). "AXL signaling has emerged as an important pathway contributing to tumour progression, metastasis, and therapy resistance." (PMID 34638349, 2021). "AXL knockout in tumor cells also promoted antigen presentation through increased MHCI expression, leading to an enhanced CD8+ T cell response." (PMID 34830794, 2021). "To identify the prognostic value of AXL, we determined differential changes in gene expression of the tumor samples assigned to either the AXLlow or the AXLhigh group." (PMID 33570712, 2021). "Treatment with inhibitory anti-AXL monoclonal antibodies YM327.6S2 or 12A11 inhibited tumor growth in a NSCLC xenograft model." (PMID 34830794, 2021). "Treatment with an antibody against active AXL or siRNA/shRNA AXL knockdown also provided anti-tumor activity in NSCLC models." (PMID 34830794, 2021). "The interactions between the tumor and host immune cells in the tumor microenvironment can induce the expression of AXL and GAS6 to promote a cancerous microenvironment." (PMID 34778071, 2021). "Further research is needed to discover biomarkers that will help identify benefits to patients and evaluate tumour responses to AXL-targeted therapies." (PMID 34638349, 2021). "In our preclinical study, we investigated the anti‐tumor effect of two AXL inhibitors, bemcentinib and tilvestamab, in vitro and in orthotopically implanted 786‐0 RCC cells in mice." (PMID 34877810, 2021). "Here, we have provided experimental evidence that dual AXL and TGFβ blockade elicit a strong anti-tumor activity in a preclinical and ex vivo human CRC model." (PMID 33570712, 2021). "AXL is a receptor tyrosine kinase with a role in cancer that has been suggested to be tumor-promoting." (PMID 33921908, 2021). "The broad role of AXL in tumour biology is the reason why its inhibition sensitizes tumours to a broad spectrum of anti-cancer drugs." (PMID 34638349, 2021). "Genetic deletion of AXL resulted in up to 20-fold enhanced T-cell infiltration and sensitization of tumor cells to radiotherapy and checkpoint immunotherapy of a transgenic mouse model." (PMID 34778071, 2021). "It seems that in tumour cells, AXL signaling is activated via a mechanism similar to that operating during efferocytosis, when GAS6 ligand binds PtdSer on the membranes of dying cells and apoptotic bodies." (PMID 34638349, 2021). "AXL increases tumor cell invasion and metastasis by promoting T cell exclusion, acting as an inducer of tumor cell plasticity." (PMID 34778071, 2021). "Immunofluorescence staining of sections from human HCC tissues revealed that AXL expression was primarily located on tumor vessels expressing CD31." (PMID 34123800, 2021). "Therapeutic interventions induce cell death in bulks of the tumours, and thereby promote AXL activation in subpopulations of AXL-expressing cells." (PMID 34638349, 2021). "A previous study showed that AXL regulates tumor invasion through the transcriptional activation of SLUG in HCC cells." (PMID 34123800, 2021). "The AXL antibody hMAb173 induced apoptosis of renal carcinoma cells and inhibited tumor growth by 78% in vivo." (PMID 34830794, 2021). "Activation of PI3K/AKT leads to endothelial cell survival and uncontrolled tumor growth, and it has been previously reported that AXL activation was required for VEGF-A-dependent endothelial cell migration and tube formation." (PMID 34884986, 2021). "In our study, we provide clear evidence of the ability of both bemcentinib and tilvestamab to significantly inhibit AXL activation and subsequent orthotopic tumor growth in vivo." (PMID 34877810, 2021). "The tumor microenvironment can regulate AXL expression in various cells, and AXL seems to have a potential role in tumor development, progression, and metastasis." (PMID 34778071, 2021).
tumor (continued). "In cellular assays, INCB081776 effectively blocked autophosphorylation of AXL or MERTK with low nanomolar half maximal inhibitory concentration values in tumor cells and Ba/F3 cells transfected with constitutively active AXL or MERTK." (PMID 33425754, 2020). "The development of new anti-AXL agents is always active, but even if preclinical studies have produced encouraging results in multiple tumor contexts, there is still a long way to go in clinical trials." (PMID 33182542, 2020). "While using a PDX model, it was shown that interfering with AXL through pharmacological inhibition resulted in an anti-tumor activity with reduced tumor cell invasiveness and reduced tumor metastatic burden." (PMID 32210163, 2020). "Next, we measured the intensity of Ki67 staining in tumor tissues, and the results indicated that the group treated with AXL-CAR-T cell with coexpressing C7R had dramatically lower intensity of Ki67staining than the other two groups." (PMID 31998790, 2020). "In the tumor microenvironment, AXL signaling is activated through multiple mechanisms to promote tumor progression." (PMID 33374832, 2020). "The results showed that in MDA-MB-231 tumor-bearing mice, AXL-CAR-T cells that coexpressed C7R presented higher proliferation levels than AXL-CAR-T cells, and the CD8 : CD4 ratio was significantly higher." (PMID 31998790, 2020). "On the other hand, while AXL-low-expressing tumor cells are highly sensitive to osimertinib, a small population of these cells demonstrates tolerance due to the increased expression and phosphorylation of IGF-1R." (PMID 32929081, 2020). "At the same time, hMENAΔv6 promotes tumor receptor overexpression, supporting the GAS6/AXL axis involvement in tumor progression." (PMID 33182542, 2020). "In this regard, activation of AXL contributes to several fundamental mechanisms of malignancy by promoting cancer cell migration and invasion, enhancing tumor angiogenesis, and facilitating cancer cell survival and tumor growth." (PMID 33425754, 2020). "Using immunofluorescence, we found that YAP1 downstream effectors identified in mRNA analysis, ANKRD1, AMOTL2 and AXL were increased in LATS1/2 cKO tumours." (PMID 32404936, 2020). "Tumours derived from the AXL-high clone contained high levels of p-AXL and AXL compared with those from the H1299 cells." (PMID 32051483, 2020). "More recently, PDXs with low AXL and high AXL expression were used to demonstrate the anti-tumor activity of DCC-2036, a novel AXL/MET inhibitor." (PMID 32210163, 2020). "LY2801653 also inhibited the growth of MET and AXL‐independent cells at higher but clinically relevant doses through decreased angiogenesis and M2 macrophages in the tumor microenvironment." (PMID 34766112, 2020). "Nevertheless, 30 days si‐XIST treatment lead to a 50% reduction in the volume of tumor, while AXL inhibitor treatment lead to a decrease of 29%, suggesting that other AXL‐independent pathways played critical roles." (PMID 32061057, 2020). "In support of AXL involvement in tumor growth, IHC analysis indicated increased Ki67 staining demonstrating increased cell proliferation in the tumors depleted of AXL." (PMID 33283192, 2020). "Some clinicopathological features, including age, tumor stage, and lymph node status in EAC patients were significantly associated with both AXL and c-ABL protein expression, demonstrating an identical clinicopathological association profile." (PMID 32922529, 2020). "The therapeutic effect of enhanced AXL-CART cells on solid tumors with larger tumor volume will be explored in our future research." (PMID 31998790, 2020). "The data analysis revealed 26 tumor samples with matching high expression of both AXL and c-ABL out of 53 total samples." (PMID 32922529, 2020). "According to the described functionalities, AXL can be considered an important mediator in the metastatic process; its high levels correlate with tumor stage and cancer progression and are essentially identified in distal metastasis." (PMID 33182542, 2020).
tumor (continued). "AXL is overexpressed in various cancers and promotes tumor metastasis and tumorigenesis, which is also known to be inhibited by miR-34a." (PMID 33374832, 2020). "AXL signaling in tumor cells is tightly controlled by various regulators, such as epigenetic and tumor microenvironment regulators." (PMID 33374832, 2020). "In these samples, we detected both inter- and intra-tumor heterogeneity regarding the number of tumor cells expressing AXL." (PMID 31963783, 2020). "AXL promotes tumor cell self‐renewal, EMT, and drug resistance, and it has become a novel attractive molecular target for anti‐neoplastic drug discovery." (PMID 32673448, 2020). "Dysregulated activation of AXL can regulate the tumor release of paracrine factors involved in processes such as inflammation, migration and immune cell recruitment." (PMID 33182542, 2020). "AXL was also observed to be essential for metastasis of these tumors as well as metastasis from the highly metastatic mouse 4T1 tumor model." (PMID 32148495, 2020). "Transplantation of an AXL-high clone isolated from H1299 cells into SCID/Beige mice induced faster development of bigger tumour than bulk H1299 cells, whereas transplantation of the AXL-low clone yielded no tumours." (PMID 32051483, 2020). "The contribution of AXL to CSCs was also confirmed in Lu99 cells and H1703-AXL cells: treatment with siAXL-1 and siAXL-2 significantly reduced the proportions of tumour spheres to 61.1% and 21.2%, respectively, in Lu99 cells." (PMID 32051483, 2020). "Several studies have shown that the inhibition of AXL promotes an anti-tumor microenvironment more responsive to therapies." (PMID 33182542, 2020). "Pharmacogenomic analysis, conducted in TNBCs, has shown that a class of dopamine receptor antagonists mimics a condition similar to AXL depletion, resulting in tumor growth and invasive capacity reduction." (PMID 33182542, 2020). "There are tumor groups with high or low AXL expression, which had different capabilities of invading vessels and forming distal metastases." (PMID 32673448, 2020). "Nevertheless, in the AXL-low-expressing tumor cells, through increased protein expression and phosphorylation of IGF-1R by osimertinib exposure (e.g., for 3 days), tolerance emerged via epigenetic modification." (PMID 32929081, 2020). "MET and AXL receptor tyrosine kinase (AXL) molecules, which are highly expressed in tumor cells, have been suggested as therapeutic targets for sunitinib-resistant RCC." (PMID 33374949, 2020). "Precisely, we linked miR-148b to GL21.T 18, a previously well characterized aptamer able to bind AXL, a tyrosine kinase receptor with oncogenic functions, overexpressed on many tumor cells." (PMID 32174798, 2020). "Immunohistochemical analysis of aggressive chemo-resistant TNBC samples obtained before treatment reveals inter- and intra-tumor heterogeneity of the percentage of AXL expressing tumor cells, and a preference of these cells to be in contact with the stroma." (PMID 31963783, 2020). "AXL signaling has also been shown to contribute uniquely to both tumor intrinsic and microenvironmental immunosuppression and is initiated by its ligand Gas6 as well as heterodimerization with other RTKs." (PMID 35582229, 2020). "In AXL-low-expressing tumor cells, EGFR and IGF-1R bind constitutively and to each protein associated with their adaptor proteins, including Gab1." (PMID 32929081, 2020). "The Gas6/AXL signaling pathway is related to tumor cell growth, invasion, metastasis, epithelial mesenchymal transition (EMT), angiogenesis, and so forth." (PMID 32673448, 2020). "We found that AXL was commonly expressed in heterogeneous patterns in clinical tumor samples, indicating that cell states in melanoma are also highly heterogeneous in patients." (PMID 32770055, 2020).